HAP1 (huntingtin associated protein 1)
Diseases named in the same sentence as HAP1 in open-access papers (continued):
Sharing a sentence is not in itself a finding about the gene and the disease.
schizophrenia (3 papers, 2011 to 2012). A major psychotic disorder characterized by abnormalities in the perception or expression of reality. "Firstly, the interaction of the schizophrenia candidate gene PCM1 and HAP1, huntingtin-associated protein 1, has been confirmed." (PMID 21298101, 2011).
cervical tumor (2 papers, 1998 to 2020). "A study was made of the relationship between the intrinsic radiosensitivity of human cervical tumours and the expression of the DNA repair enzyme human apurinic/apyrimidinic endonuclease (HAP1)." (PMID 9820167, 1998).
Iron Deficiency (2 papers, 2020 to 2023). "Under conditions of iron deficiency, Hap1 switches from an activator to a repressor of ERG genes." (PMID 37750721, 2023).
myeloid leukaemia (2 papers, 2016 to 2023). "Loss of either of these complexes resulted in decreased growth rate of Hap1 myeloid leukaemia cells in culture and sensitivity to acid stress, indicating that these were potentially novel targets in the treatment of cancer." (PMID 27519690, 2016). "Hence, the role we have found for the AP-3 complex in supporting growth of Hap1 myeloid leukemia cells under conditions of acid stress could be related to its role in lysosome biogenesis and trafficking of LAMPs, processes that might already be partially compromised in these cells." (PMID 27519690, 2016).
neuroblastoma (2 papers, 2019 to 2021). Neuroblastoma (NB) is the most common solid, extracranial childhood tumor. "(A) Nuclear extract (NE), and cytosolic extract (CE) were purified from human neuroblastoma SH-SY5Y cells and the protein fractions were analyzed by western blots (WBs) to detect HTT, ATXN3, PNKP, and HAP1 levels in these sub-cellular fractions." (PMID 30994454, 2019).
pancreatic cancer (2 papers, 2022 to 2024). "Diagnostic and therapeutic potential has been reported for HAP1 in breast and pancreatic cancer, but its role in thyroid cancer needs further study." (PMID 35459137, 2022). "For example, in the pancreas, HAP1 is consistently expressed in pancreatitis and normal pancreatic tissues but is significantly decreased or undetectable in pancreatic cancer tissues." (PMID 38975245, 2024). "The expression of HAP1 is much lower in tumor tissues of breast, gastric, and pancreatic cancers than in normal tissues and benign proliferative tissues such as polyps." (PMID 38975245, 2024).
acute lymphoblastic leukemia (1 paper, 2023). Leukemia with an acute onset, characterized by the presence of lymphoblasts in the bone marrow and the peripheral blood. "HAP1 has been implicated in various types of cancer, including gastric cancer, acute lymphoblastic leukemia (ALL), breast cancer, and lung cancer." (PMID 37685866, 2023).
Angelman syndrome (1 paper, 2025). A neurogenetic disorder characterized by severe intellectual deficit and distinct facial dysmorphic features. "HAP1 accumulation increases autophagy influx in Angelman syndrome mice, and HAP1 is one of the UBE3A substrates." (PMID 40076922, 2025).
Arrhythmia (1 paper, 2021). Any cardiac rhythm other than the normal sinus rhythm. "Our analysis reveals 5 common 7-SNV haplotypes (Hap1–5) with 2 combinations associated with life-threatening arrhythmia—Brugada syndrome (the risk Hap1/1 and protective Hap2/3 genotypes)." (PMID 33948580, 2021). "In this case, however, it appears that, as a group, these SNVs are not major contributors to the association, as they can also be observed in homozygosis (as in Hap1/1) in Hap1/2 or Hap2/2 but without association to arrhythmia." (PMID 33948580, 2021).
autism (1 paper, 2024). Persistent deficits in social interaction and communication and interaction as well as a markedly restricted repertoire of activity and interest as well as repetitive patterns of behavior. "From a mechanistic point of view in autism, the activity of TGFB signaling genes is tightly linked to mTOR, whose increased expression affects TSC1 (a partner of HAP1) linked to autism neuropathology." (PMID 38994948, 2024). "In neurons, we observed DNA hypermethylation (5-mc) of the same promoter region of HAP1 in patients with autism (>200%)." (PMID 38994948, 2024). "However, we found a significant decrease in the 5-hmC level (i.e., relatively more 5-mC) of the HAP1 promoter region flanking a progesterone binding site (CGCCCGCGC) in the astrocytes of patients with autism vs. controls (~50%)." (PMID 38994948, 2024). "Furthermore, HAP1 promoter DNA methylation was increased in the postmortem brains and neurons of patients with autism vs. controls." (PMID 38994948, 2024). "In postmortem brain samples, we found DNA hypomethylation of TGFB2 and IFI16 promoter regions, but DNA hypermethylation of HAP1 and SLC1A2 promoters in autism." (PMID 38994948, 2024). "In addition to proinflammatory genes, there are also reports of reduced expression of several key neuronal genes such as RELN, SLC1A2, GAD1, TSC1 and HAP1 in autism or autism spectrum disorders, which have not been causally linked to neuro-inflammation in autism." (PMID 38994948, 2024). "Moreover, the astrocytes of patients with autism exhibited higher expression of TGFB1 and TGFB2 but reduced expression of proliferator genes such as CXCR4 and NURR1 in addition to RELN, EN2, HAP1, SIRT1, and GPX1 vs. controls." (PMID 38994948, 2024).
Autoimmunity (1 paper, 2026). The occurrence of an immune reaction against the organism's own cells or tissues. "Hap‐1 is the unique WAI‐B2 allele showing autoimmunity phenotype." (PMID 41147414, 2026).
bladder tumor (1 paper, 2025). "To determine whether APOBEC3A or APOBEC3B was the predominant deaminase, we compared our BKPyV infection models of urothelial carcinogenesis and patient bladder tumor data to a Hap1 cell line model [with overexpression of APOBEC3A or APOBEC3B in isolation]." (PMID 41337590, 2025).
brain ischemia (1 paper, 2024). Diminished or absent blood supply to the brain caused by obstruction (thrombosis or embolism) of an artery resulting in neurologic damage. "HAP1 is proposed as a promising therapeutic target for the treatment of cerebral ischemia." (PMID 38975245, 2024). "Oxygen/glucose deprivation (OGD) can be used to construct a whole-brain ischemia model, and in this model, the recirculation of the GABAAR β3 subunit, the interaction between GABAAR and HAP1, and the total protein level of HAP1 are decreased." (PMID 38975245, 2024).
breast tumors (1 paper, 2023). "However, only a small proportion of the A3A-like group of breast tumors exhibit a percentage of APOBEC3 signature mutations in YTCW motifs that approaches the level inflicted by A3A here in the HAP1-TK-M9 system (i." (PMID 38033156, 2023). "As regards A3A, the majority of breast tumors have ≤72.7% APOBEC3 signature mutations in YTCW motifs, which is the overall preference of A3A here in the HAP1-TK-M9 system suggesting the involvement of at least one other A3 enzyme." (PMID 38033156, 2023).
brucellosis (1 paper, 2026). Brucellosis is a bacterial infection that spreads from animals to people via unpasteurized dairy products or by exposure to contaminated animal products or infected animals. "Through haplotype analysis, Hap3 and Hap5 were identified as being associated with brucellosis resistance when compared to Hap1 (p<0.05)." (PMID 41856082, 2026).
Brugada syndrome (1 paper, 2021). A genetically heterogeneous condition characterized by complete or incomplete right bundle branch block accompanied by ST elevation in leads V1-V3. "Third, we cannot exclude the possibility that rare variants co-evolving with Hap1 are the ultimate contributors to Brugada syndrome." (PMID 33948580, 2021). "Hap1 and Hap9 differ in only 1 allele (at rs1), and Hap1/9 is less abundant in Brugada syndrome cases than in controls." (PMID 33948580, 2021). "Hap1 is substantially more abundant in Brugada syndrome cases than controls—initially counterintuitive, as Hap1 harbors the major allele in each rs1–7 position (Fisher’s exact test: p = 6.86e−14, 1KG-NFE; p = 9.41e−14, Wellderly-NFE; and p = 5.63e−13, GTEx-NFE)." (PMID 33948580, 2021). "Based on the remaining n = 83 Brugada syndrome cases, we validated Hap1–6 and Hap8." (PMID 33948580, 2021). "First, it is based on a relatively small number of cases that we pre-selected for not carrying rare deleterious variants in the coding regions of the SCN5A gene (the latter decision may have helped us to identify the link of Hap1/1 and Hap2/3 to Brugada syndrome)." (PMID 33948580, 2021). "Notably, Hap1–3 are associated with Brugada syndrome, with more than half of the cases carrying the Hap1/1 genotype, whereas none of the cases carries the Hap2/3 genotype." (PMID 33948580, 2021). "Notably, the Hap1/1 genotype is uncommon in the EAS super-population, which is consistent with epidemiologic studies showing that Brugada syndrome cases across the Chinese, Japanese, Taiwanese, and South Korean populations carry fewer deleterious variants than Caucasians in the SCN5A locus." (PMID 33948580, 2021).
diabetes mellitus (1 paper, 2024). A metabolic disorder characterized by abnormally high blood sugar levels due to diminished production of insulin or insulin resistance/desensitization. "In pathology, HAP1 is associated with a variety of diseases, such as neurological diseases, cancers, and diabetes mellitus." (PMID 38975245, 2024). "An increasing number of studies have revealed that the expression and function of HAP1 are associated with various diseases, including nervous system disorders, cancer, and diabetes." (PMID 38975245, 2024). "HAP1, a class of proteins tightly associated with Htt, may also contribute to the disruption of insulin vesicle transport and insulin secretion in HD-associated diabetes." (PMID 38975245, 2024). "In conclusion, further exploration to decipher the association between HAP1 and T2DM will provide new therapeutic directions for diabetes mellitus and other related endocrine diseases." (PMID 38975245, 2024). "In addition, HAP1 has been proved to participate in cancers and diabetes mellitus." (PMID 38975245, 2024).
Ebola (1 paper, 2017). "Several HAP1 screens have used replication-competent, recombinant vesicular stomatitis viruses (rVSV) encoding orthogonal glycoproteins to discover cellular factors required for the entry of highly pathogenic viruses, including Ebola, Andes, and Lassa viruses." (PMID 28388693, 2017).
enthesitis (1 paper, 2026). Inflammation at the site of insertion of ligaments, tendons, and other fibrous structures into bone. "Specifically inhibiting SOX5 in enthesis fibroblasts via rAAV9.HAP-1 carrying a shRNA targeting Sox5 blocked the generation of SDC1+ sheath fibroblasts in response to mechanical strain and markedly reversed the development of CXCR4hi neutrophil-mediated enthesitis." (PMID 41637585, 2026).
epilepsy (1 paper, 2024). A brain disorder characterized by episodes of abnormally increased neuronal discharge resulting in transient episodes of sensory or motor neurological dysfunction, or psychic dysfunction. "Huntingtin-associated protein 1 was shown to regulate seizure by controlling the activity of GABAAR in animals with pentylenetetrazole (PTZ)-induced epilepsy." (PMID 38975245, 2024). "In epilepsy, disruption of the HAP1/14-3-3 complex reduces the strength of GABAAR-mediated inhibition of synaptic transmission." (PMID 38975245, 2024). "Elucidating the critical role of HAP1 in influencing inhibitory synaptic responses in epilepsy is relatively important, as HAP1 may serve as a promising therapeutic target for epilepsy." (PMID 38975245, 2024).
Fanconi anemia (1 paper, 2020). Fanconi anemia (FA) is a hereditary DNA repair disorder characterized by progressive pancytopenia with bone marrow failure, variable congenital malformations and predisposition to develop hematological or solid tumors. "However, while published screens only identified individual and different Fanconi anemia-associated genes to be essential in HAP1 cells, we could identify all members of the core complex and associated genes involved in interstrand crosslink repair to be essential in HAP1 cells." (PMID 33228647, 2020). "Further, HAP1-specific essential genes were enriched for components of various complexes of the Fanconi anemia pathway." (PMID 33228647, 2020). "Since the generation of HAP1 FANCG and FANCM knockout cell lines has also been reported recently, loss of expression of Fanconi anemia-associated genes might rather slow down cellular proliferation than directly inducing cell death." (PMID 33228647, 2020).
fibromyalgia syndrome (1 paper, 2024). "A genome-wide association study of fibromyalgia syndrome revealed a significant association between pain and the HAP1 gene, with HAP1-deficient mice exhibiting mechanical allodynia and nociceptive hypersensitivity suppression in both acute and chronic pain models." (PMID 38975245, 2024).
glioblastoma (1 paper, 2023). The most malignant astrocytic tumor (WHO grade IV). "To this end, we performed 2 biological replicates of CAPture-MS from 3 × 107 Jurkat (T cell leukemia) and U251 (established glioblastoma [GBM] cell line) and compared these proteomes with those of HAP1 and HEK293T centrosomes." (PMID 37852252, 2023).
hepatoma (1 paper, 2020). "Similar to our finding in Hap1 cells, loss of Spring in murine Hepa1-6 hepatoma cells and in primary mouse hepatocytes attenuated activity of the SREBP pathway." (PMID 32111832, 2020).
HIV-1 infection (1 paper, 2021). The type species of lentivirus and the etiologic agent of acquired immunodeficiency syndrome (AIDS). "We found that HAP1 SUN1, SUN2, or SUN1/SUN2 knockout cells were permissive to HIV-1 infection, suggesting that this system is not providing evidence for a functional contribution of SUN1 or SUN2 to HIV-1 infection." (PMID 34580332, 2021).
Infertility (1 paper, 2016). "This speculation is further supported by the more severe infertility in the upf3-1;HAP1/hap1-2 mutant plants." (PMID 26867216, 2016).
lung squamous cell carcinoma (1 paper, 2024). "For example, 13–45% of the 100 most down-regulated genes in HAP1 were also deregulated in prostate adenocarcinoma, lung squamous cell carcinoma, and skin cutaneous melanoma when comparing patients with and without the PAPSS2-PTEN locus deletion." (PMID 37984988, 2024).
Machado-Joseph disease (1 paper, 2020). "STB/HAP1 can also interact with the causal agents of some other polyQ diseases, such as with Abelson helper integration site 1 in Joubert syndrome, ataxin 3 in Machado-Joseph disease and TATA binding protein in spinocerebellar ataxia type 17." (PMID 33089002, 2020).
malaria (1 paper, 2015). Malaria is a serious and sometimes fatal disease caused by a parasite that commonly infects a certain type of mosquito which feeds on humans. "The distribution of the haplotypes Hap3 and Hap4 were significantly different between malaria (+) and malaria (−) groups, while the Hap1 and Hap2 were similar between the groups." (PMID 25627396, 2015).
malnutrition (1 paper, 2014). Inadequate nutrition resulting from poor diet, malabsorption, or abnormal nutrient distribution. "This notion was supported by the finding that transgenic mice deficient in HAP1, suffer from postnatal malnutrition and morbidity because of a dysfunction in feeding behavior." (PMID 25071696, 2014).
neuritis (1 paper, 2023). A neuropathy arising from inflammation of one or more nerves. "HAP1 and proBDNF form a complex with sortilin to be engaged in Golgi-endosome transport, preventing proBDNF degradation and modulating its targeting to endosomes, microtubules, and neuritis." (PMID 36824265, 2023). "The kinesin-dependent APP axonal transport is affected by HAP1 in neurons, and lack of HAP1 decreases the transport of APP vesicles from the cell body to neuritis." (PMID 36824265, 2023).
neuropathic pain (1 paper, 2024). Chronic pain caused by damage to nerve fibers. "HAP1 deficiency (HAP1 ± mice) reduces mechanical allodynia and heat hyperalgesia while also attenuating the hyperexcitability of DRG neurons in these neuropathic pain models." (PMID 39472517, 2024).
non-small cell lung carcinoma (1 paper, 2020). A group of at least three distinct histological types of lung cancer, including non-small cell squamous cell carcinoma, adenocarcinoma, and large cell carcinoma. "Independent validations on NUMA1-proficient HAP1 and non-small cell lung cancer cell lines exposed to BMI1 inhibition by PTC-318 or BMI1 knockdown resulted in cell death following mitotic arrest." (PMID 32343689, 2020).
ovarian carcinoma (1 paper, 2004). A malignant neoplasm originating from the surface ovarian epithelium. "In conclusion, we present the first evidence that serum HAP1 is significantly increased in early-stage ovarian cancer patients." (PMID 15199385, 2004). "The identity of HAP1 was further confirmed by 2-DE Western blotting on the serum from healthy volunteers and grade 1 and 3 ovarian cancer patients using monoclonal anti-human haptoglobin antibody that binds to an epitope within HAP1." (PMID 15199385, 2004). "We suggest that HAP1 may constitute a new and useful biomarker for ovarian cancer diagnosis." (PMID 15199385, 2004).
poliovirus infection (1 paper, 2019). An disease or disorder caused by infection with Enterovirus C. "Statistically significant reductions in poliovirus infection in both Hap1 and A549 TNK2 knockout cells and reduction in enterovirus D68 infection in A549 cells were also observed (E F)." (PMID 31769754, 2019). "In addition, independent Hap1 cells deficient in WASL had reduced EMCV, CVB3 and poliovirus infection (B C)." (PMID 31769754, 2019).
proteinopathies (1 paper, 2018). "The interaction of DDX49 with proteins known to be involved in neurological disorders such as Huntingtin-associated protein 1 (HAP1) and Amyloid-beta protein APP suggests that DDX49 might also have a role in diverse proteinopathies." (PMID 29618122, 2018).
stress-related disorder (1 paper, 2020). Stress-related disorders are mental health disorders that are a result of an atypical response to both short and long-term anxiety due to physical, mental, or emotional stress. "Although further investigation is required to explore this possibility, our findings suggest that Hap1 is a promising candidate for investigating the pathogenesis of stress-related disorders that are associated with hypothalamic dysfunction." (PMID 32581713, 2020).
thyroid cancer (1 paper, 2022). "In conclusion, we developed a novel seven-mRNA (CDKN2A, FGF7, CTSB, HAP1, DAPK2, DNAJB1, ITPR1) risk model and nomogram that could help assess the prognosis of patients and guide clinical decision-making and individualized therapy for differentiated thyroid cancer." (PMID 35459137, 2022).
uveal melanoma (1 paper, 2022). A melanoma derived from melanocytes of the uveal tract. "We treated isogenic HAP1-KO MBD4 and HAP1-WT cell lines with camptothecin, doxorubicin, gemcitabine, cytarabine, paclitaxel, and dacarbazine, an alkylating agent commonly used to treat uveal melanoma patients (together with its active form, MTIC)." (PMID 36323843, 2022).